STK11 (serine/threonine kinase 11)
Diseases named in the same sentence as STK11 in open-access papers (continued):
Sharing a sentence is not in itself a finding about the gene and the disease.
lung adenocarcinoma (continued). "In addition, in KRAS-mutant lung adenocarcinoma, STK11/LKB1 inactivation induced immunosuppressive TME and innate resistance to PD-1 inhibitors through downregulation of PD-L1 in tumor cells and effector T-cell exclusion." (PMID 35884355, 2022). "As an example, when we searched the database for genetic changes in the STK11 gene (encoding LKB1) in human cancers, it was found to be quite frequently mutated or deleted, particularly in lung adenocarcinoma where this occurred in 15–20% of cases (as indeed had already been reported)." (PMID 36383046, 2022). "In lung adenocarcinoma (LUAD), serine/threonine kinase 11 (STK11) and Kelch-like ECH-associated protein 1 (KEAP1) co-mutant status strongly predict poor survival, which is associated with significantly elevated ferroptosis-protective gene expression and less vulnerability to ferroptosis." (PMID 35399527, 2022). "The need for rigorous and accurate characterization of STK11 functional status is now urgent as clinical decisions governing the use of anti-PD-1 monoclonal antibody therapy for patients with KRAS-driven lung adenocarcinoma have come to depend upon accurate STK11 functional evaluation." (PMID 34849607, 2021). "Consistent with known COSMIC STK11 tumor‐specificity (mutations present in 11% of lung adenocarcinomas but only 1% of ductal carcinomas), relatively high levels of STK11 mutations were observed in lung, but not breast samples." (PMID 32940377, 2020). "Mutations in cancers other than HCC associated with a negative outcome for ICI treatment include inactivating mutations in JAK1/2 or beta-2-microglobulin in melanoma, MDM4 amplifications, or EGFR alterations in different stage IV tumors or STK11/LKB1 alterations in KRAS-mutant lung adenocarcinoma." (PMID 33353145, 2020). "Finally, yet importantly, STK11/LKB1 alterations have been described as a major driver of primary resistance to PD-1 blockade in KRAS-mutant lung adenocarcinoma." (PMID 31612108, 2019). "Type I and II LCNECs harbor key genomic alterations and oncogenic mutations, which are commonly found in SCLC, lung adenocarcinoma or squamous cell carcinoma (e.g., in RAS genes, BRAF, NFE2L2, as well as in STK11 and KEAP1 in the case of type I LCNECS, and RB1 losses in the case of type II LCNECs)." (PMID 29535388, 2018). "In lung adenocarcinoma, the serine/ threonine kinase STK11 (also called LKB1) is a frequently mutated tumor suppressor gene that has been identified as the main driver of the inert immune-cold phenotype, despite the presence of a paradoxically high TMB due to LKB1 deficiency." (PMID 39107856, 2024). "However, co-mutations may alter such efficacy, such as KRAS-mutant patients with STK11 or KEAP1, as co-mutations have a poorer prognosis for immunotherapy than KRAS wild-type lung adenocarcinoma patients." (PMID 36675641, 2023). "STK11 mutations are commonly found in lung adenocarcinoma, but not in other sporadic tumors." (PMID 35621648, 2022).
lung adenocarcinoma (continued). "Skoulidis and colleagues showed that STK11/LKB1 mutation is associated with less expression of PD-L1 and decreased infiltrative CTL density, resulting in primary resistance to PD-1-based immunotherapies in both human and murine STK11/LKB1-deficient lung adenocarcinoma." (PMID 36189283, 2022). "KRAS/STK11 co-mutation might drive intrinsic resistance to PD-1/PD-L1 inhibitors, as it was the only marker associated with PD-L1 negativity among 924 intermediate/high TMB lung adenocarcinoma patients." (PMID 35251972, 2022). "For example, in 230 cases of lung adenocarcinoma studied by The Cancer Genome Atlas (TCGA) network, the PRKAA1 gene was amplified in 22 (10%), while the STK11 gene (encoding the upstream kinase LKB1) was subject to either deletions, or mutations expected to cause loss-of-function, in 43 (19%)." (PMID 33375416, 2020). "In lung adenocarcinomas, we recapitulate the mutual exclusivity between KRAS and EGFR as well as the importance of TP5328, for which our model suggests that it is frequently co-mutated with both KRAS and others like MLL3, as well as KRAS and STK11 are frequently co-mutated." (PMID 30341300, 2018). "However, cBioPortal reveals that, in the same cancer genome studies where STK11 is mutated or deleted, the PRKAA1 gene encoding α1 is often amplified, with the highest frequency (10–15%) also occurring in lung adenocarcinomas (note the preponderance of red bars)." (PMID 26934201, 2016). "Included in the panel were the cell lines A549 (lung adenocarcinoma) and BxPC-3 (pancreatic adenocarcinoma), which have been previously shown to be particularly sensitive to the growth-inhibitory effects of metformin because of mutations in LKB1 (STK11)(A549) or mitochondrial complex I (BxPC3)." (PMID 27959931, 2016). "In addition, given that LKB1 functions in part to prevent CREB target gene activation, the decreased mutation frequency of STK11 (LKB1) in TTP-low lung adenocarcinomas compared to the TTP-high cohort corresponds with the observed decrease in CREB-target gene expression in TTP-low tumors." (PMID 25541715, 2014). "FDA-emerging biomarkers were present in both histologies, with genes like STK11, KEAP1, and others more frequently altered in lung adenocarcinoma." (PMID 39664186, 2024). "There is a report that the therapeutic effect of programmed death-(ligand) 1 (PD-1/PD-L1) inhibition was diminished in STK11- and KEAP1-mutant lung adenocarcinoma." (PMID 36107353, 2022). "Examples were NSD1 in HNSC, CTNNB1 in liver hepatocellular carcinoma (LIHC), and STK11 and KEAP1 in lung adenocarcinoma (LUAD)." (PMID 29125844, 2017). "STK11 and KEAP1 mutations were associated with worse outcomes to immunotherapy in KRASmut but not in KRASwt lung adenocarcinoma." (PMID 38866964, 2024).
lung adenocarcinoma (continued). "Because Teffs lack well‐balanced effector functions, their infiltration into a setting characterised by KRAS, STK11/Lkb1, KEAP1 and other oncogene mutant‐bearing advanced lung adenocarcinomas is severely reduced, and the rate of glutamine uptake by tumour cells is significantly increased." (PMID 38468489, 2024). "Patient#B was a 53-year-old male, current smoker, with a lung adenocarcinoma TTF1+ PDL1 0% without EGFR, KRAS, or BRAF mutation or ALK and ROS1 translocation but STK11 mutation." (PMID 37370798, 2023). "In relation to this, dMMR and MSI-H have a high predictive value, while somatic mutations such as STK11/LKB1 and KEAP1 are prognostic of poor outcomes but not predictive in terms of response to therapies with checkpoint inhibitors in lung adenocarcinoma." (PMID 33322522, 2020). "Mutation or loss of STK11 is associated with low or absent PD-L1 expression, in both KRAS-mutant and KRAS-wild type lung adenocarcinoma, and with impaired efficacy of ICIs targeting the PD-1/PD-L1 axis." (PMID 33114576, 2020). "In lung adenocarcinoma, KEAP1 and STK11 mutations are associated with the non-T cell-inflamed phenotype." (PMID 33106165, 2020). "The two most common non-oncogene-driven mutations in lung adenocarcinoma, STK11 (serine/threonine kinase 11) and KEAP1 (Kelch-like ECH-associated protein 1) mutations, were found to be predictors of poor outcomes in patients with NSCLC treated with immunotherapy." (PMID 40650126, 2025). "Then, they examined the relationship between the PIWIL1 expression and mutations in lung adenocarcinoma, and eventually found that the PIWIL1 expression was remarkably higher in patients who did not have serine/threonine kinase 11 (STK11) or hepatocyte growth factor (HGF) mutations." (PMID 31890151, 2019). "mTOR pathway may be activated in lung adenocarcinomas through three different molecular mechanisms: PI3KCA mutations, STK11 mutation associated or not with low levels of LKB1." (PMID 30060526, 2018). "Although the present study did not assess the KEAP1 and/or STK11 gene alterations and the detailed types of adenocarcinomas, above‐mentioned reports might partially explain why TTF‐1 negative lung adenocarcinoma showed worse outcomes with ICI monotherapy in our study." (PMID 35808895, 2022).
breast cancer (257 papers, 2008 to 2025). A primary or metastatic malignant neoplasm involving the breast. "Several clinical trials are currently conducting ICI therapies in STK11-mutated breast cancer, including all subtypes of patients." (PMID 41051525, 2025). "A case report documented a near-complete response in a patient with metastatic breast cancer harboring a somatic STK11 point mutation following treatment with the mTOR inhibitor everolimus." (PMID 41051525, 2025). "To evaluate the in vivo effects of STK11 loss, we established an orthotopic breast cancer model in immunocompetent female mice." (PMID 41051525, 2025). "Although the incidence of STK11 mutation is relatively low in breast cancer patients, it has been associated with an increased odds ratio for poor overall survival." (PMID 41051525, 2025). "In breast cancer, STK11 is considered a syndromic gene, and pathogenic germline variants of STK11 are observed in 0.0087% of unselected breast cancer patients." (PMID 41051525, 2025). "According to the MSK-IMPACT® database from cBioPortal, STK11 mutations, including missense, truncating, in-frame shift, splice, and fusion alterations, are detected in only 59 of 3116 (1.9%) breast cancer patients." (PMID 41051525, 2025). "Pathogenic variants in the FANCI, MET and STK11 have been reported in association with breast cancer." (PMID 37277882, 2023). "The metabolic reprogramming that occurs under LKB1 loss is also observed in a Her2 positive Lkb1 mutant breast cancer mouse model, Stk11−/−/NIC." (PMID 35573694, 2022). "Individuals with pathogenic germline STK11 variants have a lifelong elevated risk to acquire various types of malignancies, such as gastrointestinal, pancreatic, testicular, cervical and breast cancer, that mainly manifest themselves during adulthood." (PMID 36824296, 2022). "The pathogenic variants of PTEN, CDH1, and STK11 were very rare, so they had a limited contribution to Chinese breast cancer." (PMID 34606182, 2021). "The pathogenic variants of PTEN, CDH1, and STK11 were too rare in our study to estimate their risks of breast cancer in Chinese women, which suggested that these genes had a very limited contribution to breast cancer in unselected Chinese women." (PMID 34606182, 2021). "Traditionally, STK11 alterations in breast cancer, observed at 1%–2% in this study, have been associated with Peutz‐Jeghers syndrome and have not, to date, been linked to resistance to ICPI treatments." (PMID 33314633, 2021). "The mutation frequency of ERCC8 (0.3%) in breast tumors was also similar to some of the other known breast cancer susceptibility genes such as STK11 (0.3%) and LSP1 (0.3%)." (PMID 33277540, 2020). "High lifetime breast cancer risk has been established for STK11 and PTEN gene mutations that are causative for dominantly inherited hamartomatous polyposis syndromes, Peutz‐Jeghers and Cowden syndrome, respectively (Couch, Nathanson, & Offit, 2014)." (PMID 32949222, 2020). "Functional inactivation or loss of STK11 was shown to promote breast cancer initiation and progression to metastasis." (PMID 30054559, 2018). "There are also 23 PubMed publications reporting the association between STK11 with breast cancer and “Breast Carnicoma” is the most frequent label in these publications." (PMID 30598097, 2018). "The analogous analysis of the breast cancer subset of the MSK-IMPACT study found that mutations in both STK11 and PIK3CB tended to be mutually exclusive with PTEN mutations, but was not statistically significant." (PMID 29566768, 2018). "Loss of STK11 expression increases migration and invasion in breast cancer, while a STK11 knock-out predisposed mice to prostatic intraepithelial neoplasia." (PMID 27014907, 2016).
breast cancer (continued). "It is challenging to obtain sufficient STK11-mutated breast cancer patients for the study." (PMID 41051525, 2025). "Our findings suggest that targeting STK11-associated immunosuppressive mechanisms may provide a novel therapeutic option for STK11-deficient breast cancer patients." (PMID 41051525, 2025). "Furthermore, the low prevalence of STK11 mutations in breast cancer remains a significant limitation." (PMID 41051525, 2025). "Moreover, we employed an orthotopic breast cancer model in immunocompetent mice to explore the immunological consequences of STK11 loss." (PMID 41051525, 2025). "All cases were either confirmed carriers or obligate carriers of likely pathogenic or pathogenic germline variant in STK11.There were 34 breast cancers in 27 patients (including five bilateral synchronous tumors, one case with bilateral metachronous tumors, and one metachronous unilateral tumor)." (PMID 40317347, 2025). "Given their contribution to immune evasion, targeting PMN-MDSCs may represent a potential therapeutic strategy to defeat resistance to immune checkpoint inhibitors in STK11-deficient breast cancer." (PMID 41051525, 2025). "Deletion of NUAK1 or STK11 (encoding LKB1) was each identified as synthetic lethal with PTEN loss in breast cancer, and loss of either NUAK1 or STK11 drives a requirement for increased NFκB activity in ovarian cancer, again linked to suppression of oxidative stress." (PMID 36975767, 2023). "Putative duplications overlapping the breast cancer tumour suppressor gene STK11 suggested decreased risk of breast cancer in our study for both BRCA1 carriers (HR = 0.49, 95%CI 0.29–0.81, p = 5.4 × 10−3) and BRCA2 carriers (HR = 0.44, 95%CI 0.22–0.88, p = 9.2 × 10−3)." (PMID 36203093, 2022). "Furthermore, mutations in the PTEN genes, which cause Cowden syndrome, and serine/threonine kinase 11 (STK11), which identifies as a causative gene in Peutz‐Jeghers syndrome, have been linked to an increased risk of breast cancer." (PMID 35762299, 2022). "Notably, pathogenic germline variants of PTEN, CDH1, and STK11 were extremely rare in Chinese breast cancer patients or controls." (PMID 34606182, 2021). "In addition, pathogenic variants of PTEN (5 cases), CDH1 (1 case), and STK11 (1 case and 1 control) were too rare to estimate their risks of breast cancer in Chinese women." (PMID 34606182, 2021). "We observed a difference in the ATP levels between STK11−/−/NIC mammary tumors and WT mammary tissue, reflective of the loss of LKB1 expression and therefore regulation of AMPK activity, leading to hyperactivation of mTOR through both mTORC1 and mTORC2 pathways." (PMID 23451056, 2013). "Since mammary tumors from STK11−/−/NIC mice are positive for elevated ErbB2 expression, and 31% of HER2 positive breast cancers show loss of LKB1 expression, we investigated the effect of a next generation small molecule that targets the EGFR (ErbB1) and HER2, BIBW2992 (BIBW), on mTOR signaling." (PMID 23451056, 2013). "However, the hypothesis that the STK11/LKB1 gene is causative of familial breast cancer syndrome has already been tested by germline mutaion screening in Swedish breast cancer families." (PMID 19077293, 2008).